IGFBP3 (insulin like growth factor binding protein 3)
Diseases named in the same sentence as IGFBP3 in open-access papers (continued):
Sharing a sentence is not in itself a finding about the gene and the disease.
cancer (continued). "IGFBP-3 has not only direct antitumor functions in human cancers, but also anti-inflammatory properties in normal cells through the activation of a specific receptor, IGFBP-3R." (PMID 36430216, 2022). "For example, IGFBP3 overexpression upregulates p21 in some cancer cells, and inhibition of PAI-1 activity reduces p16 expression." (PMID 35401669, 2022). "Consistent with the in vitro expression evidence, ribosomal dysfunction enhanced the survival-linked ERK1/2 signals, downregulating expression of the anticancer-related IGFBP3 in cancer cells under chemotherapeutic action." (PMID 33972671, 2021). "This suggests that cancer cells with more invasive abilities and low IGFBP3 tend to activate HIF-2α." (PMID 34824343, 2021). "Because elevation of ALDH activity has been considered a CSC marker in various cancer types, we evaluated the effect of IGFBP-3 on the regulation of ALDH activity by using a red fluorescent ALDH substrate (Aldered 588-A)." (PMID 33801272, 2021). "The proapoptotic, antiangiogenic, and antimetastatic activities of insulin-like growth factor binding protein-3 (IGFBP-3) through IGF-dependent or -independent mechanisms have been suggested in various types of human cancers." (PMID 33801272, 2021). "This study is unique because it involved cancer cells with a known degree of invasiveness, which is correlated with IGFBP3, and the studies of hypoxic events were in a chronological sequence." (PMID 34824343, 2021). "Given the antiproliferative, proapoptotic, antiangiogenic, and anti-adhesion effects of IGFBP-3 in a variety of cancer cells, we postulated the antimetastatic activity of IGFBP-3 in NSCLC and HNSCC." (PMID 33801272, 2021). "IGFBP-3 has been reported to be a binding partner of retinoic receptors (RXR and RAR), where these receptors are essential for IGFBP-3-induced apoptosis in cancer cell lines, and for the inhibitory effect of IGFBP-3 on preadipocyte maturation." (PMID 34502376, 2021). "The TGF‐β type V receptor (TβR‐V) mediates growth inhibition by IGFBP‐3 and TGF‐β in epithelial cells and loss of TβR‐V expression in these cells leads to development of carcinoma." (PMID 34485840, 2021). "Transformation of wild‐type CHO epithelial cells into CHO‐LRP‐1−/− cells (carcinoma cells) appeared to greatly upregulate non‐specific (IGFBP‐3‐independent) PPase activity in these CHO‐LRP‐1−/− cells." (PMID 34485840, 2021). "We found that DMU-214 caused a significant increase in mRNA expression of IGFBP3 and KLF4, which have been reported to inhibit cancer cell migration as well as proliferation." (PMID 32046103, 2020). "Recent reports further explored the therapeutic potential of the IGFBP-3/IGFBP-3R axis in cancer by developing an IGFBP-3R agonistic monoclonal antibody (mAb)." (PMID 32443727, 2020). "Cancer research has shown evidence that the IGFBP-3 gene is vulnerable to epigenetic regulation, including DNA methylation and histone modification." (PMID 31570976, 2020). "Lastly, we show that an IGFBP-3 Fc construct in combination with EGFR targeted therapy augments inhibition of cancer cells both in vitro and in vivo." (PMID 32066763, 2020). "The objective of this review is to present a comprehensive overview of the relationship between IGFBP7 and cancer, as well as highlighting IGFBP3 crosstalk with IGFBP7 reported in recent studies." (PMID 32500027, 2020). "The impact of resveratrol to reduce IGF-1 and IGFBP-3 in the blood indicated that the drug has an impact on cancer and the development of cancer." (PMID 32961987, 2020). "Analysis of IGFBP-3 expression identified highly variable expression levels among different types of cancer as well as normal tissues." (PMID 32443727, 2020). "Some data suggest that higher levels of IGFBP3, the main IGF-binding protein, are associated with an increased risk of cancer, while others support an inverse association." (PMID 33260481, 2020).
cancer (continued). "Further differential expression of IGFBP-3 was analyzed in cancers and the counterpart normal tissues where at least 12 normal samples were available." (PMID 32443727, 2020). "Since then, there has been an intensive investigation toward characterizing the molecular and cellular mechanisms for IGF/IGF-IR-independent antitumor effects of IGFBP-3 in human cancer in vitro and in vivo." (PMID 32443727, 2020). "In the same datasets, TMEM219 expression also showed variable expression patterns, but had less variation when compared to IGFBP-3 among different types of cancer as well as normal tissues." (PMID 32443727, 2020). "For instance, in cancer research, the IGFBP-3 gene is described to be vulnerable to epigenetic regulation, including DNA methylation and histone modification." (PMID 31570976, 2020). "The ability of IGFBP-3 CPPs to specifically target cancer cells is a major advantage in comparison with other CPPs." (PMID 32478064, 2020). "In cancer cells, IGFBP3 internalization was shown to be mediated by either caveolae or clathrin endocytic pathway via binding to transferrin/transferrin receptor complexes." (PMID 31951594, 2020). "In particular, IGF/IGF-IR-independent actions of IGFBP-3 have been extensively investigated and their involvement in initiation and progression of various cancers has been recognized." (PMID 32443727, 2020). "In an early era of IGFBP-3 research in cancer, many studies demonstrated that IGFBP-3 is upregulated by different types of cell growth inhibitors at the transcriptional level in a variety of human cancer cells." (PMID 32443727, 2020). "Any changes on the IGF axis arising from IGF-I or IGFBP-3 imply valuable data on the use of these proteins as possible markers to measure chemo-effective impact towards cancer." (PMID 32961987, 2020). "Apart from well-documented pro-apoptotic and growth-inhibitory functions of IGFBP3, evidence is emerging that it exhibits also pro-survival and growth-promoting properties in a variety of cancers." (PMID 31951594, 2020). "A tight regulation of IGFBP-3 signaling is not only essential for cancer treatment but also during bone development as shown by both Igfbp3 transgenic and knock-out mouse models." (PMID 29445126, 2018). "Of the genes that HHV-6A sequences were found to be integrated into or located near, most were significantly associated with cancers, and six, including CPLX1, IGFBP3, and the oncogene SH3RF2, were associated with malignant tumor formation (p = 8.45 × 10−7)." (PMID 30542640, 2018). "Taken together, these data revealed that an oxidative stress management network (SLC3A2, SLC7A5, and IGFBP3) under the control of p19-VHL performs an oncogenic role by overriding apoptosis in cancer stem cells." (PMID 28580172, 2017). "SphK1 mediates insulin-like growth factor binding protein-3 (IGFBP-3) growth factor signaling in breast cells, where overexpression of IGFBP-3 is associated with cancer progression." (PMID 28415564, 2017). "Further this study highlights the clinical significance of MTA1, DNMT3a and IGFBP3 in determining an overall poor prognosis of cancer patients." (PMID 28393842, 2017). "The robust expression of IL-6, IGFBP-3, and serpinE1 following coculture with obASCs would suggest that these cancer cells are more aggressive." (PMID 29527228, 2017). "Aberrant expression or regulation of IGF1 and IGFBP3 has been demonstrated to facilitate carcinogenesis and have an effect on cancer prognosis." (PMID 27976731, 2016). "Many studies have reported that high levels of IGF-I, low levels of IGFBP-3, or increments of the molar ratio of IGF-I/IGFBP-3 were associated with various types of cancers." (PMID 27094973, 2016). "IGFBP-3 has also been reported to have antiproliferative 24, antimetastatic 25, and proapoptotic effects 26 in a variety of cancer cells." (PMID 25914189, 2015).
cancer (continued). "These previous findings and the ability of IGFBP-3 to regulate the expression of integrins, including α3, β1, and β4, indicate that IGFBP-3 would play a major role in cancer development and progression." (PMID 25945837, 2015). "Based on these evidences and our results, we focused the integrin β4 as an attractive target for anti-angiogenesis and cancer therapy and examined the effect of IGFBP-3 on integrin β4." (PMID 25945837, 2015). "We and others have demonstrated that IGFBP-3 is a potent inducer of apoptosis in a variety of human cancer cell types by inhibiting IGF-mediated signaling pathways." (PMID 25945837, 2015). "In cancers where IGFBP-3 induces apoptosis, an increase in its expression in response to DNA damage would be clinically advantageous." (PMID 26378048, 2015). "Given the diverse connection between IGFBP3 and cancer phenotypes, the functional roles of IGFBP3 in tumorigenesis and lymph node metastasis of OSCC remain vague." (PMID 26540630, 2015). "Because IGFBP-3 can inhibit cancer progression by inhibiting angiogenesis and the metastatic activities of cancer cells, IGFBP-3 was expected to affect cancer and/or vascular endothelial cell-matrix adhesion." (PMID 25945837, 2015). "Consistent with this idea, IGFBP-3 is more highly expressed in certain chemo- or radiosensitive cancer cell lines than in matched resistant cell lines, as shown in cervical carcinoma and ovarian and lung cancer cells." (PMID 26221601, 2015). "Several cancer studies have described aberrant hypermethylation in CpG islands of the IGFBP3 promoter as one of the mechanisms responsible for IGFBP3 gene silencing." (PMID 24964199, 2014). "Given the context-dependent, multimodal effects of unliganded IGFBP3, mechanistic studies in well-defined cancer cells are therefore needed." (PMID 25374561, 2014). "There are several data indicating that IGFBP3 can play an inhibitory role in the PI3K/Akt signalling pathway in different types of cancer cells, through an IGF-independent effect." (PMID 25294954, 2014). "The IGFBP3 and F3 genes showed limited differences in expression levels within cancer epithelial cell samples, when comparing delta Ct values from different biopsies originating from the same patient." (PMID 25296164, 2014). "Previously, it has been reported that IGFBP3 promotes cancer cell growth via an IGF-independent manner." (PMID 24920244, 2014). "IGFBP-3 has been reported to decrease significantly in the blood serum of patients affected by certain cancers." (PMID 24905466, 2014). "A number of studies have reported that epigenetic modifications such as DNA methylation and histone acetylation play important roles in IGFBP3 gene silencing in several human cancers." (PMID 24964199, 2014). "In this comparison, IGFBP3 consistently provided values similar to the Diff (delta Ct) within the primary and secondary cancer samples from each patient." (PMID 25296164, 2014). "Insulin-like growth factor binding protein 3 (IGFBP-3) plays an important role in the development and progress of cancers." (PMID 23527244, 2013). "Dysregulation of IGFBP3 expression and hypermethylation of its promoter have been observed in many cancers." (PMID 24019942, 2013). "In this study we have expanded our view of long-range interactions in cancer by exploring the genome-wide interaction profile of IGFBP3." (PMID 24019942, 2013). "As for the IGF-independent actions, IGFBP-3 can induce antiproliferative and proapoptotic effects in human cancer cells." (PMID 24143239, 2013).
cancer (continued). "A few studies have confirmed that IGFBP-3 levels are influenced by the -A202C IGFBP3 polymorphism, and this polymorphism could influence responsiveness to growth inhibitors whose action involves up-regulation of IGFBP3 and the efficacy of various agents proposed for cancer chemoprevention." (PMID 23527244, 2013). "IGFBP-3, a major serum carrier protein for IGFs, is a multi-functional protein known to inhibit cellular growth and induce apoptosis of various cancer cells." (PMID 23833672, 2013). "A previous study proposed that higher IGF1 serum levels and lower IGFBP3 levels were associated with cancer risk; however, the intra-individual variability in circulating IGF1, IGF2, and IGFBP3 levels is genetically determined." (PMID 22347413, 2012). "The IGF-1 pathway, whose genes IGF1R, IGF-1 and IGFBP-3 are among the target genes of the differentially expressed miRNAs, plays a critical role in cancer development, including ES." (PMID 22429812, 2012). "At high concentrations, for example, as have been observed in cancer microenvironments, IGFBP-3 release can serve a beneficial role by inducing apoptosis of cancer cells, restoring tissue homeostasis." (PMID 22792172, 2012). "Up-regulation of IGFBP3 has been observed in response to a variety of anti-cancer agents, including celecoxib." (PMID 19903356, 2009). "A reduction in the amount of IGFBP3 available results in an increase in levels of free IGF-1, a factor associated with growth, proliferation, and an elevated risk of several cancers." (PMID 19603096, 2009). "Dual functions of IGFBP3 have been reported previously in cancers of the renal cells, esophagus, breast, colon, and prostate, as well as in endothelial cells." (PMID 19903356, 2009). "IGFBP3 expression is lost in many cancer cells, and reintroduction of the protein often results in cell death." (PMID 19903356, 2009). "In cancer tissue, however, IGFBP-3 mRNA was elevated and this reflected increased expression in the stroma but diminished or absent expression in malignant epithelium." (PMID 18498652, 2008). "The contribution of locally expressed IGFBP-3 to pre-malignant and malignant lesions in the colon is not well understood and few studies have evaluated tissue expression of IGFBP-3 in relation to cancer development and progression." (PMID 18498652, 2008). "A recent study compared IGFBP-3 mRNA levels and protein localization in grossly normal versus nearby malignant colonic tissue from the same cancer patient." (PMID 18498652, 2008). "Scientists have contributed to investigating the correlation of serum IGF-1 or IGFBP-3 to the prevalence of a variety of cancers, but have given diverse results." (PMID 18781172, 2008). "The decreased IGFBP3 expression observed in our study of cancer tissues is consistent with these cancer-inhibitory effects of IGFBP-3." (PMID 17210081, 2007). "Reduced expression of IGFBP3 in the prostate epithelium is correlated with cancer progression from HGPIN to localised cancer and androgen-independent disease." (PMID 17453001, 2007). "Promoter hypermethylation of IGFBP3 likely occurs as a subsequent epigenomic ‘hit’ in the multi-step process of cancer development." (PMID 17453001, 2007). "The genes common to the top ends of the lists for the outcomes of the three cancers studied here include those originally used by Singh and Gordon for outcome prediction, such as IGFBP3." (PMID 17411443, 2007). "The reduced expression of IGFBP3 in cancer tissues is consistent with the role of IGFBP-3 in cancer inhibitory effects." (PMID 17210081, 2007). "QRT–PCR revealed that the three cancer cell lines expressed IGFBP3 relative to the normal cell line PWR-1E, however, pharmacological demethylation of LNCaP increased the expression of IGFBP3 several hundred-fold." (PMID 17453001, 2007).
cancer (continued). "There is now accumulating evidence that IGFBP-3 has an important anti-proliferative and pro-apoptotic role in the regulation of cancer cell growth." (PMID 16600019, 2006). "The level and pattern of IGFBP3 expression in nodular hyperplasia was similar to that seen in normal prostate tissues, and significantly different from the expression seen in cancer samples (p = 0.0036 and p < 0.00001 respectively)." (PMID 15318950, 2004). "The study findings suggest (albeit indirectly) that serum IGF-I and IGFBP-3 levels normalise after smoking cessation, an observation that is clearly relevant to cancer prevention." (PMID 15354219, 2004). "In the normal breast epithelial cells, IGFBP-3 is a potent survival factor and proliferative agent, while in the cancer cells, IGFBP-3 is an inhibitor of cell growth and accentuates cell death triggered by various agents." (PMID 12085194, 2002). "Advancement-stage cancers (Group III) showed a higher prevalence of theC2 IGFBP3+ and C3 HHATL+ subtypes, with IGFBP3 being linked to apoptosis resistance and HHATL-mediated hedgehog signaling, which might increase stemness." (PMID 41383633, 2025). "IGFBP-3 signaling participates in the pathogenesis of cancer." (PMID 39272080, 2024). "Recent research has confirmed that IGFBP3 acts as a key regulator in cancer development and progression, which could regulate aerobic glycolysis through the PI3K/AKT pathway." (PMID 39636180, 2024). "Several inhibitors for cell growth in human cancer cells increase IGFBP-3 expression." (PMID 39272080, 2024). "The observed anti-proliferative and pro-apoptotic functions of IGFBP-3 may provide insight into its significance in the pathophysiology and etiology of various human diseases, including cancer, diabetes, vascular disease, asthma, and growth disorders." (PMID 37253773, 2023). "The observed decrease in circulating IGF-I and IGFBP-3 might contribute to cancer chemopreventive activity”." (PMID 35270803, 2022). "IGFBP3 was identified to promote apoptosis in cancers through several ways." (PMID 35871161, 2022). "In addition, these cells express dickkopf-3 (DKK-3), dickkopf-1 (DKK-1), and insulin-like growth factor-binding protein 3 (IGFBP-3), which significantly inhibit the proliferation of cancer cells and increase the apoptosis rate of HepG2 cells." (PMID 35406638, 2022). "Furthermore, stimulating cancer cells with recombinant IGFBP-3, IGFBP-2, VEGF, PDGF-AA or IL-31 led to upregulation of ET1 and ETA." (PMID 36241617, 2022). "Therefore, it is difficult to decide the ultimate outcome of either growth inhibition or cytoprotection of IGFBP3 in cancer progression." (PMID 35945453, 2022). "Previous studies indicated that there might be potential clinical value of IGFBP3 in several forms of cancers." (PMID 36409444, 2022). "In this section, we showed that FASN could modulate PDGF-AA and IGFBP-3 secretion to affect lymphangiogenesis, which will hopefully lead to the identification of more messengers in the communication between cancer cells and HLECs." (PMID 35597782, 2022). "Higher expression level of IGFBP-3 mRNA was detected in normal colon than in cancer." (PMID 36013453, 2022). "Also, heightened differences were observed between IGF-I and IGFBP-3 levels in control participants compared to enrollees who had a higher T stage; revealed cancer of the lymph nodes; and demonstrated evidence of metastases." (PMID 35198099, 2022).